CD74 (CD74 molecule)
Diseases named in the same sentence as CD74 in open-access papers (continued):
Sharing a sentence is not in itself a finding about the gene and the disease.
Sepsis (16 papers, 2009 to 2025). Sepsis is defined as life-threatening organ dysfunction caused by a dysregulated host response to infection. "We used the training cohort and the test cohort to explore the independence and diagnostic value of SET, LPIN1, TXN, and CD74 for sepsis." (PMID 37346041, 2023). "Four ERRGs, namely SET, LPIN1, TXN, and CD74, have been identified as characteristic diagnostic biomarkers for sepsis." (PMID 37346041, 2023). "At birth, CD74, either associated with IP-10 or clinical criterion, had the best accuracy in prognosing sepsis mortality." (PMID 36509812, 2022). "In our study, CD74 expression alone has a low accuracy for neonatal sepsis diagnosis, but its association with IP-10, the interferon-γ inducible protein-10, emerges as a good combination of biomarker." (PMID 36509812, 2022). "In high-risk patients, CD74/IP-10 ratio was found to have a good accuracy for neonatal sepsis diagnosis, depicting a novel signature for defective Th1 response and altered antigen presentation seen in sepsis and sepsis-associated immune depression." (PMID 36509812, 2022). "The expression of CD74 was significantly decreased in the sepsis-associated group, which might be associated with the excessive inflammatory response." (PMID 36405762, 2022). "The underlying pathophysiologic rational behind the association of low CD74/low mHLA-DR in infants and sepsis mortality may be resumed by an altered antigen presentation, either acquired or secondary to a perinatal event." (PMID 36509812, 2022). "Interestingly, in the sub-group of high-risk patients CD74/IP-10 ratio was shown for the first time to have a better accuracy for sepsis diagnosis than any studied biomarkers and clinical combinations." (PMID 36509812, 2022). "In Astrocyte 1, inflammation-associated genes (GFAP, FOS, C3, CD74) were significantly upregulated, while BBB-related genes (GRIA2, NRGN, TXNIP) were downregulated in sepsis." (PMID 41030458, 2025). "Using the same model in mice, CD74 ablation protected against sepsis-induced cardiomyopathy, providing further evidence that MIF promotes cardiomyopathy in sepsis." (PMID 40092999, 2025). "CD47-amyloid-β-CD74 signaling is a key driver of adaptive immunosuppression in sepsis, suppressing B cells and impairing immunity." (PMID 40185975, 2025). "The expression profiles of SET, LPIN1, and CD74 were significantly lower in the sepsis patients, whereas the expression of TXN was much higher." (PMID 37346041, 2023). "Based on the expression profile of SET, LPIN1, TXN, and CD74, two molecular subgroups of sepsis were obtained with K = 2, with 375 samples in cluster A and 385 samples in cluster B." (PMID 37346041, 2023). "The association analysis illustrated notable relationships between four ERRGs (including SET, LPIN1, TXN, and CD74) and sepsis." (PMID 37346041, 2023). "Expression analysis of four diagnostic biomarkers suggested that the sepsis samples in cluster A had higher expression of SET, LPIN1, and CD74; however, the expression of TXN was remarkably higher in cluster B." (PMID 37346041, 2023). "CD74/IP-10 ratio value of 0.44 (Youden index 0.21) had a sensitivity of 73% and specificity of 25% for clinical sepsis diagnosis." (PMID 36509812, 2022). "Nevertheless, while acting as a receptor, Neutrophils connected with plasma cells by up-regulating MIF-(CD74+CD44) (strong) in both sepsis and control group, but connected with CD8+ T cell, NK cell, B cell, and DC by down-regulating MIF-(CD74+CD44) in both sepsis and control group." (PMID 39108261, 2024). "Various research had indicated that CD74 was expressed abnormally in inflammatory disorders, whereas its role in sepsis was still unknown." (PMID 37346041, 2023). "In addition, a nomogram model was developed to explore the diagnostic effectiveness of the expression profiles of SET, LPIN1, TXN, and CD74 for sepsis in both cohorts." (PMID 37346041, 2023).
Sepsis (continued). "The expression of CD74 in the sepsis-related group was significantly inhibited, which may be one of the reasons for the excessive activation of inflammatory cells." (PMID 36405762, 2022). "Interestingly, in our study, infants surviving sepsis showed a prolonged alteration of CD74 expression up to 1 month following EONS." (PMID 36509812, 2022). "Therefore, we cannot conclude from the current results that a decreased CD74 mRNA expression is a marker of immunosuppression in sepsis." (PMID 24321376, 2013). "However, investigations into the function of the APP → CD74 axis in sepsis remain limited." (PMID 40625751, 2025). "Conversely, in the sepsis group, the probability of cellular communication between NKT and CD16Mono via MIF - (CD74+CXCR4) exhibited the highest magnitude." (PMID 40375981, 2025). "In the training and test cohorts, we observed that the expression profiles of SET, LPIN1, and CD74 were significantly higher in the healthy group, whereas the expression of TXN was much higher in the sepsis group." (PMID 37346041, 2023). "Through PCR analysis, it was found that levels of CD74, LPIN1, and SET were significantly decreased after sepsis in rats, whereas the level of TXN was significantly increased after sepsis in rats, which was consistent with the results of bioinformatics." (PMID 37346041, 2023). "Another supportive fact for our study was that the mRNA expression levels of CD74, LPIN1, and SET were downregulated in rats with sepsis, whereas TXN was upregulated." (PMID 37346041, 2023). "Notably, the MIF–(CD74+CXCR4), HLA–KIR, ANXA1–FPR2, and CD99–CD99 signaling pathways were significantly upregulated in sepsis." (PMID 41346577, 2025). "Although well recognized in cancer, few publications relate CD74 utility in sepsis, none in children and neonates." (PMID 36509812, 2022). "Nevertheless, such prolonged post-sepsis reduction in CD74 transcription, as well as reduced mHLA-DR has never been described in both infants and adults." (PMID 36509812, 2022). "Additionally, the APP → CD74 signaling axis and the RPA1-centered regulatory network warrant in-depth experimental exploration to evaluate their potential as targets for therapeutic intervention in sepsis." (PMID 40625751, 2025). "Indeed, patients who do not survive sepsis have decreased HLA-DRA, -DMA, -DMB, and CD74 mRNA expression in whole blood and reduced HLA-DR expression on the cell surface of circulating monocytes." (PMID 19903332, 2009).
atherosclerosis (15 papers, 2011 to 2025). A disease characterized by the build-up of fatty material and calcium deposition in the arterial wall resulting in partial or complete occlusion of the arterial lumen. "Our findings also show, for the first time, that CD74 is associated with increased levels of apoptosis and ferritin in macrophages, TR, and atherosclerosis-related lipid metabolism." (PMID 35050177, 2022). "Previous studies have shown that CD74 is associated with cancer and inflammatory disease, such as Helicobacter pylori infection, bladder inflammation, atherosclerosis and renal injury." (PMID 21379381, 2011). "It has also been reported that deficiency of CD74 reduces atherosclerosis in mice." (PMID 35050177, 2022). "In mice, it has been showed that deficiency of CD74 reduces atherosclerosis." (PMID 35050177, 2022). "This study suggests that CD74 in apoptotic macrophages is linked to inflammation and thrombosis in progression of human atherosclerotic plaques, lipid metabolism, and clinical manifestation in atherosclerosis." (PMID 35050177, 2022). "This study further investigated whether CD74 expression is related to apoptosis in human carotid atheroma and in macrophage apoptosis induced by 7keto, an atheroma relevant oxysterol that has been implicated in chronic inflammation of atherosclerosis." (PMID 35050177, 2022). "Furthermore, CD74 in apoptotic macrophages induced by oxidized lipids may be associated with ferritin levels and lipid metabolism in atherosclerosis." (PMID 35050177, 2022). "MIF binding to receptors (CD74/CD44, CXCR4) activates downstream signaling pathways (ERK1/2, NF-κB, AKT), mediating pro-inflammatory responses implicated in aortic aneurysm, atherosclerosis, rheumatoid arthritis, and systemic lupus erythematosus." (PMID 41383630, 2025). "Crucially, we demonstrate that secretory VSMCs act as key microenvironmental regulators, driving M1 polarization via MIF secretion and CD74 activation, potentially amplifying inflammatory cascades in atherosclerosis." (PMID 41383630, 2025). "Moreover, it will be interesting to determine whether atherosclerotic plaque‐associated macrophages, which have increased expression of MHCII and CD74 genes, are derived from DCMo, and whether there is any link between increased DCMo and the risk of atherosclerosis during aging." (PMID 36040389, 2022). "Cathepsin S inhibitors and siRNA targeting the regulation of CD74 function have also made progress in animal models of atherosclerosis or cardiac I/R injury." (PMID 36712241, 2022). "In term of mechanism, CD74 deficiency impairs APC antigen presentation and T-cell activation, which reduces atherosclerosis." (PMID 36712241, 2022). "The characteristics of high expression of CD74 in atherosclerosis and acute MI and the rapid endocytosis of CD74 provide an essential basis for the precise targeting of CD74 for treatment." (PMID 36712241, 2022). "Of these, CXCL9, CXCL10, CCL5, CCL8, CRCL2, Cd74 and IRF8 have previously been implicated in atherosclerosis." (PMID 25478796, 2014). "Therefore, upon treatment with Milatuzumab (an anti‐CD74 antibody) in mice, macrophages are the predominant cellular target of the antibody in the context of atherosclerosis." (PMID 40548932, 2025). "Blocking CD74 disrupts migrasome‐mediated signaling, attenuating atherosclerosis progression." (PMID 40548932, 2025). "Surface CD74 in apoptotic macrophages and ferritin production induced by oxidized lipids may contribute to inflammation and plaque vulnerability in atherosclerosis." (PMID 35050177, 2022).
atherosclerosis (continued). "Based on our in vitro and clinical pathology data, we suggest that surface CD74 in apoptotic macrophages and inflammatory ferritin induced by oxidized lipids may contribute to inflammation, thrombosis, and plaque vulnerability in atherosclerosis." (PMID 35050177, 2022). "Thus, CD74 may be a potential therapeutic target for atherosclerosis by reducing inflammatory response, which require further preclinical study to validate." (PMID 36712241, 2022). "First, CD74 participates in T-cell antigen presentation independently of MIF and MIF2, and T-cells play an important role in atherosclerosis." (PMID 36712241, 2022). "However, whether CD74 expression is associated with apoptosis in atherosclerosis has not yet been studied." (PMID 35050177, 2022). "We demonstrated that MIF is a functional ligand of chemokinereceptors CD74 and CXCR4 and that it participates in the regulation of monocyterecruitment in atherosclerosis promoted by P.gingivalis infection." (PMID 30506423, 2019). "Finally, re-analysis of scRNA-seq data highlighted the expression patterns of TIMP-1 and CD74 in human atherosclerotic lesions, thus, together with our experimental data, indicating a role for the TIMP-1–CD74 axis in vascular inflammation and atherosclerosis." (PMID 37508563, 2023). "While our focus was on inflammatory/atherosclerosis-relevant cellular effects of MIF predominantly mediated by the MIF chemokine receptor axis, it is possible that MIF/CXCL4L1 heterocomplexation also affects MIF signaling responses through CD74." (PMID 36094626, 2022). "Together with the identified TIMP-1 and CD74 expression patterns in re-analyzed scRNA-seq datasets from atherosclerotic plaques of carotid endarterectomy (CEA) patients, our study suggested a novel role for the TIMP-1–CD74 axis in vascular inflammation and atherosclerosis." (PMID 37508563, 2023). "MIF not only interacts with CD74, but also engages in high affinity interactions with the chemokine receptors CXCR2 and CXCR4 to drive inflammatory leukocyte recruitment processes and may mediate the inflammatory pathogenesis of experimental atherosclerosis." (PMID 22506003, 2012). "TIMP1 treatment further increased pSTAT3 levels in CD74+, but not in CD74−, proliferating VSMCs, providing in vivo evidence linking this signaling pathway to the initiation of VSMC proliferation in atherosclerosis." (PMID 39215134, 2024).
hepatocellular carcinoma (15 papers, 2015 to 2026). A malignant tumor that arises from hepatocytes. "CD74 deficiency was also investigated in hepatocellular carcinoma and rendered similar results, yielding reduced proliferation and a reduced number of tumors in the CD74−/− mice compared with the WT controls." (PMID 36672343, 2023). "Similar results were observed in hepatocellular carcinoma, where CD74 deficiency led to reduced proliferation and a decreased tumor number in CD74 − / − mice compared to the wild-type controls." (PMID 37880655, 2023). "Similarly, hepatocellular carcinoma (HCC) exhibits strong associations between CD74 expression, immune infiltration, and response to immunotherapy." (PMID 41597203, 2026). "The interaction of MIF and CD74 was reported to exert proproliferative and antiapoptotic effects in murine hepatocellular carcinoma." (PMID 35634447, 2022). "In this context, recent research associated CD74+ (major histocompatibility complex II-associated invariant chain, MHC-II) macrophages with favorable prognosis and immune contexture in hepatocellular carcinoma." (PMID 34829862, 2021). "Furthermore, CD36+ cancer-associated fibroblasts (CAFs) employ MIF and CD74 to attract CD33+ myeloid-derived suppressor cells (MDSCs), creating an immunosuppressive environment that facilitates immune evasion in hepatocellular carcinoma." (PMID 40051627, 2025). "Additionally, high expression of CD74 is an independent predictor of good prognosis in patients with hepatocellular carcinoma." (PMID 40470045, 2025). "One study found that high expression of CD74 enhances the immune function of macrophages and CD8+ T cells in the tumor microenvironment of hepatocellular carcinoma." (PMID 40470045, 2025). "However, there are many gaps in the study of the prognostic value of CD74 expression and immune infiltration in hepatocellular carcinoma (HCC)." (PMID 39118044, 2024). "Moreover, the prognosis of hepatocellular carcinoma (HCC) patients with positive CD74 expression was better than that with negative CD74 expression, and it could be a biomarker of the prognosis in HCC." (PMID 37147569, 2023).
gastric cancer (14 papers, 2009 to 2025). A primary or metastatic malignant neoplasm involving the stomach. "A recent study has shown that CD74 expression in the gastric carcinoma cell line is related to H. pylori adhesion." (PMID 22838407, 2012). "A recent study has revealed that several citrus components strongly suppress CD74 (a new receptor for H. pylori urease) expression in the gastric carcinoma cell line." (PMID 22838407, 2012). "Knockdown of CD74 in gastric cancer cells significantly reduced cell proliferation." (PMID 37880655, 2023). "They found that the knockdown of CD74 or using anti-CD74 mAb could achieve the similar results in gastric cancer." (PMID 27788497, 2017). "Third, CD4 and CD74 may be used as markers to predict the prognosis of colon and gastric cancer." (PMID 27323782, 2016). "When the gastric cancer cells were treated with a combination of 4D3 and CDDP, intracellular platinum concentrations were increased to 1.5- and 1.2-times the levels seen in CD74 and TMK-1 cells, respectively, treated with CDDP alone." (PMID 31040910, 2019). "Four of these five integrations into STAD are in genes known to be up-regulated in gastric cancer, specifically CEACAM5, CEACAM6, TMSB, and CD74." (PMID 23840181, 2013). "For instance, agents against some overexpressed targets such as CD71, PTK7, CD74 and SLC44A4 could be evaluated in some conditions such as breast, colon and gastric cancer." (PMID 37740463, 2023). "Thus, as observed in prostate and gastric cancer, MIF/CD74 interactions appear to play a role in breast tumourigenesis." (PMID 19602265, 2009). "Another finding in this study is that CD4 and CD74 may be used as markers to predict the prognosis of colon and gastric cancer, but not the markers for cancer stem cell." (PMID 27323782, 2016). "However, no obvious trend was found among CD44, CD4, and CD74 mRNA in gastric cancer." (PMID 27323782, 2016). "We also identified that ADCs against CD71, PTK7, CD74, SLC44A4 and LIV‐1 were not under evaluation in breast, colorectal, prostate and gastric cancer, which suggests potential opportunities for evaluation." (PMID 37740463, 2023).
glioblastoma (14 papers, 2013 to 2025). The most malignant astrocytic tumor (WHO grade IV). "In glioblastoma, tumor-associated macrophages tended to polarize toward M2 macrophages in the high CD74 group." (PMID 39118044, 2024). "A previous report of Cd74 as a positive prognostic marker was likely due to its association with an M1-polarized immune milieu in glioblastoma." (PMID 34881090, 2021). "In addition, a higher amount of CD74-positive microglia were detected in the glioblastoma and were associated with beneficial patient survival." (PMID 34881090, 2021). "CD74 had moderate predictive accuracy in the diagnosis of glioblastoma and prediction of survival." (PMID 34540893, 2021). "CD74 has been further described as one of the most upregulated molecules in human glioblastomas." (PMID 34671548, 2021). "Differential expression patterns of CD74 and CXCR2 by MDSCs within and outside the glioblastoma TME further emphasize that MIF signaling is location-specific." (PMID 39233830, 2024). "Our data indicated that patients with high CD74 expression had more CD8+ T cells and M1 macrophages, indicating stronger antitumor activity, which differed from observations in glioblastoma." (PMID 39118044, 2024).